PHF8 (PHD finger protein 8)
Diseases named in the same sentence as PHF8 in open-access papers (continued):
Sharing a sentence is not in itself a finding about the gene and the disease.
prostate carcinoma (continued). "In prostate cancer, PHF8 was expressed in both the nuclei and cytoplasm of tumor cells." (PMID 36980457, 2023). "Our current research identified a previously unknown PHF8/FOXA2 axis in prostate cancer as well as its role in NEPC development." (PMID 33009820, 2021). "Although it is well established that PHF8 can enhance prostate cancer cell proliferation, whether PHF8 is involved in prostate cancer initiation and progression is relatively unclear." (PMID 33009820, 2021). "Importantly, we provide evidence that the levels of PHF8 in prostate cancer correlates with tumor hypoxia, Gleason grades, poor prognosis and lower overall survival and that PHF8 is functional under hypoxic conditions." (PMID 27991916, 2016). "Similarly, we observed that PHF8 mRNA was also induced by DHT treatment in VCaP prostate cancer cell line." (PMID 27991916, 2016). "Furthermore, the functional relationship between PHF8 and the AR signaling pathway and prostate cancer progression following castration treatment remain poorly understood." (PMID 27991916, 2016). "We propose that a novel regulatory axis, HIFs/PHF8/AR, exists in prostate cancer and targeting this axis could be a potential therapeutic strategy in combating castration-induced CRPC." (PMID 27991916, 2016). "Furthermore, we demonstrate that the expression of PHF8 is induced by hypoxia in prostate cancer cell lines and this induction requires HIF1α and HIF2α." (PMID 27991916, 2016). "The elevated PHF8 in turn promotes the AR signaling pathway and prostate cancer progression." (PMID 27991916, 2016). "To determine whether the levels of PHF8 in prostate cancer correlate with clinical outcome, we conducted Kaplan–Meier analyses on the follow-up data obtained from these 65 patients." (PMID 27991916, 2016). "Importantly, we observed that PHF8 is highly expressed in clinical androgen deprived prostate cancer samples and expression of PHF8 correlates with increased levels of HIF1α and HIF2α." (PMID 27991916, 2016). "As a first step of a systemic examination of the roles of PHF8 and exploration of the mechanisms in prostate cancer development, we decided to assess the relationship between PHF8 expression and different malignant stages of prostate cancer." (PMID 27991916, 2016). "Finally, we provide evidence that the levels of PHF8 in prostate cancer clinical samples correlate with increased Gleason grade, poor prognosis and lower overall survival of prostate cancer patients." (PMID 27991916, 2016). "Our study suggests that the HIFs/PHF8/AR axis is likely a driving force for prostate cancer progression and may also be a target for therapy." (PMID 27991916, 2016). "Furthermore, we demonstrate that the expression of PHF8 is induced by hypoxia in various prostate cancer cell lines." (PMID 27991916, 2016). "Having demonstrated that hypoxia can induce PHF8 overexpression in prostate cancer cell lines, we hypothesized that hypoxia in prostate cancer could be a mechanism for the increased PHF8 expression observed in clinical prostate cancer samples." (PMID 27991916, 2016). "Having established that PHF8 could be induced by hypoxia and function as an AR coactivator, we next wished to examine if PHF8 could be used as a biomarker for prostate cancer." (PMID 27991916, 2016). "Furthermore, PHF8 is overexpressed in prostate cancer with effects on cell proliferation, migration, and invasion." (PMID 24146981, 2013). "Furthermore, we provide evidence that increased PHF8 expression in prostate cancer clinical samples correlates with the severity of tumor hypoxia (pre- vs post-castration) and elevated levels of HIF1α and HIF2α and Gleason grades, poor prognosis and lower overall survival." (PMID 27991916, 2016). "However, given its potential role in regulating global histone methylation, it is also possible that PHF8 could enhance other transcriptional activation processes to promote prostate cancer progression." (PMID 27991916, 2016).
prostate carcinoma (continued). "In our analysis, twelve histone demethylases showed gene upregulation in prostate cancers, of which six (KDM1A, KDM4B, KDM5B, KDM5C, KDM7A, and PHF8) were in line with previous reports." (PMID 36776320, 2023). "We then compared the levels of PHF8 and FOXA2 in seven paired‐prostate cancer specimens collected before and after treatments with abiraterone, enzalutamide or docetaxel." (PMID 33009820, 2021). "The interplay between PHF8 and HIFs may shed light on hypoxia-induced neuroendocrine differentiation (NED) and resistance to androgen deprivation therapies in prostate cancer." (PMID 39311138, 2024). "Decreased PHF8 leads to the enrichment of H3K9me2 in the promotor region of activating transcription factor 2 (ATF2) and permits its transcription, thereby inhibiting the proliferation of prostate cancer cells." (PMID 39311138, 2024). "By comparing the transgenic adenocarcinoma of the mouse prostate (TRAMP) mice with or without Phf8 knockout, we systemically examined the role of PHF8 in prostate cancer development." (PMID 33009820, 2021). "To test this hypothesis, we cultured three prostate cancer cell lines, LNCaP, 22RV1 and DU145 under hypoxic conditions for 0, 12 and 24 h and then examined the levels of PHF8 protein by western blot analysis and mRNA by RT–PCR." (PMID 27991916, 2016). "Furthermore, since both chemical and surgical castration treatments for prostate cancer patients have been shown to correlate with local hypoxia and subsequent activation of the HIF pathway, castration is likely to further induce the expression of PHF8." (PMID 27991916, 2016).
Intellectual disability (10 papers, 2010 to 2024). "PHF8 is indispensable for developmental processes, as emphasized by the association of PHF8 variants with intellectual disabilities and craniofacial dysmorphism." (PMID 39311138, 2024). "In humans, PHF8 mutations targeting the JmjC domain have been associated to intellectual disability and craniofacial deformities." (PMID 36672913, 2023). "Systematic mutation screening of brain-expressed genes and linkage analysis of familial mental retardation have identified plant homeodomain finger protein 8 (Phf8, located in Xp11.2) as one of XLID-associated genes." (PMID 29317619, 2018). "To model mental retardation in humans with PHF8 deficiency, we generated Phf8 knockout (KO) mice by targeting the exons 7 and 8 encoding the core region of mice PHF8." (PMID 29317619, 2018). "While caution is certainly warranted considering PHF8's association with intellectual disability, it is plausible that inhibition of PHF8 in the adult modulates anxiety/depression without affecting intellectual capacity." (PMID 28485378, 2017). "Considering that behavioural abnormalities have been associated with defects of the striatum and PHF8 has been implicated in intellectual disability, we next evaluated potential behavioural phenotypes in Phf8 KO mice." (PMID 28485378, 2017). "The role of PHF8 mutations in causing mental retardation has been attributed to the inability of mutant PHF8 to activate ribosomal DNA transcription." (PMID 26464965, 2015). "Indeed, PHF8 depletion in humans is linked to intellectual disability, autism spectrum disorder, attention deficit hyperactivity disorder, and intellectual disability, while similar neurological deficits were found in Phf8-/- mice." (PMID 37718819, 2023). "Mutations in the PHF8 gene cause cognitive impairment and intellectual disability." (PMID 36052683, 2022). "Because mutation of PHF8 causes mental retardation, PHF8 might potentially be involved in the regulation of other XLMR genes." (PMID 20346720, 2010). "To address whether Phf8 knockout mice mimic the intellectual disability in patients, we evaluated the learning and memory capacity of mice." (PMID 29317619, 2018). "While PHF8 mutations have previously been associated with intellectual disability and cleft lip/palate in patients, we failed to obtain evidence for either cognitive or craniofacial abnormalities in Phf8-deficient mice maintained on a 129/B6 background." (PMID 28485378, 2017).
colorectal cancer (9 papers, 2020 to 2025). A primary or metastatic malignant neoplasm that affects the colon or rectum. "Higher expression of PHF8 has also been observed in various human cancers and has been associated with shorter survival of liver cancer, colorectal cancer, gastric cancer, and lung cancer patients." (PMID 36980457, 2023). "Strikingly, tumor PHF8 deletion stimulates a viral mimicry response in colorectal cancer cells, where the depletion of key components of endogenous nucleic acid sensing diminishes PHF8 loss-meditated antiviral immune responses and anti-tumor effects in vivo." (PMID 37454216, 2023). "PHF8 overexpression is associated with lower overall survival of colorectal cancer patients." (PMID 37454216, 2023). "Furthermore, a higher expression of PHF8 was observed in various human cancers and it was associated with poor clinical outcomes of the gastric, liver, and colorectal cancers." (PMID 36980457, 2023). "hnRNPA2B1 and PHF8 displayed high expression levels, whereas circCDYL showed low expression levels in colorectal cancer cells." (PMID 39810713, 2025). "MiR-488, a tumor suppressor, targets the 3′-UTR of PHF8 mRNA in colorectal cancer and inhibits its expression to suppress the growth and metastasis of colorectal cancer." (PMID 39311138, 2024). "Here, the authors suggest PHF8 as an epigenetic checkpoint and show that targeting PHF8 induces a viral mimicry response enhancing anti-tumour immunity in colorectal cancer." (PMID 37454216, 2023). "In this study, we identify that PHF8 functions as an immune suppressor that limits anti-tumor immunity in colorectal cancer." (PMID 37454216, 2023). "The effects of PHF8 inhibition on the suppression of cancer cells have been reported in gastric, lung, and colorectal cancer cells." (PMID 36980457, 2023). "Consistent with our findings, another study demonstrated that overexpression of miR-488 drove the progression of colorectal cancer via its regulation of plant homeo domain finger protein 8 (PHF8)." (PMID 34565283, 2021). "Taken together, our results establish that inhibition of PHF8 led to activation of antiviral immune responses and APP pathway in colorectal cancer cells." (PMID 37454216, 2023). "Ablation the function of PHF8 abrogates tumor growth, activates anti-tumor immune memory, and augments sensitivity to ICB therapy in mouse models of colorectal cancer." (PMID 37454216, 2023).
gastric cancer (9 papers, 2020 to 2025). A primary or metastatic malignant neoplasm involving the stomach. "A high expression of PHF8 is associated with an advanced tumor stage and inferior survival in gastric cancer patients." (PMID 39311138, 2024). "In contrast, a higher expression of PHF8 in gastric cancer tissue than in normal tissue was mainly observed in the cytoplasm of cancer cells." (PMID 36980457, 2023). "In HER2-negative advanced gastric cancer, PHD finger protein 8 (PHF8) positively correlates with PKCα, and high PHF8 and PKCα levels are significantly associated with poor clinical outcome." (PMID 36358843, 2022). "A MYC/miR-22-3p/PHF8 regulatory axis has been identified in gastric cancer." (PMID 39311138, 2024). "In addition, the expression of PHF8 was upregulated in gastric cancer and the overexpression of PHF8 predicted shorter OS of HER2-negative gastric cancers." (PMID 36980457, 2023). "PHF8 also physically interacts with β-Catenin and is recruited to the mesenchymal marker VIM promoter to co-activate its transcription in gastric cancer cells." (PMID 39311138, 2024). "MYC increases PHF8 protein levels rather than mRNA expression via stabilizing miR-22-3p, promoting the proliferation and migration or invasion of gastric cancer cells." (PMID 39311138, 2024). "A higher expression of PHF8 also stimulated proliferation, metastasis, and the EMT phenotype of cancer cells by activating the Wnt/β-catenin signaling in lung cancer cells and gastric cancer cells." (PMID 36980457, 2023). "Moreover, PHF8 promotes the migration and invasion of HER2-negative gastric cancer." (PMID 39311138, 2024). "In both the ICB clinical cohorts of melanoma treated with combined anti-PD-1 and anti-CTLA-441 and gastric cancer treated with anti-PD-142, responders showed significantly lower PHF8 expression levels than non-responders, suggesting that PHF8 expression was anti-correlated with ICB responses." (PMID 37454216, 2023).
Cognitive impairment (8 papers, 2014 to 2024). Abnormal cognition is characterized by deficits in thinking, reasoning, or remembering. "The epigenetic disruption of RSK-mTOR-S6K signaling is involved in cognitive defects by loss of Phf8 and that the FDA-approved mTOR inhibitor rapamycin can rescue the behavioral and LTP deficits caused by Phf8 deletion." (PMID 29317619, 2018). "Mutation of the human gene PHF8, encoding a histone demethylase, is linked to cognitive defects but its role in development is unclear." (PMID 28485378, 2017). "While mutations of PHF8 have been associated with cognitive defects and cleft lip/palate, its role in mammalian development and physiology remains unexplored." (PMID 28485378, 2017). "Clinically, mutations in PHF8 protein that render it enzymatically inactive cause severe cognitive deficits." (PMID 26464965, 2015). "PHF8 is important for proper neural development, and its mutation is associated with Fragile X syndrome, believed in part to be responsible for the associated cognitive deficits." (PMID 24735454, 2014). "However, instead of developmental deficits and cognitive impairments, anxiety and depression-like behaviors were observed in Phf8 deficient mice, which is thought to be mediated by the direct regulation of serotonin receptors (5-Hydroxytryptamine receptor 1a/2a (Htr1a, Htr2a)." (PMID 39311138, 2024). "Several cases of cognitive abnormalities and craniofacial deformities due to PHF8 genetic variations have been reported." (PMID 39311138, 2024). "Further gene linkage analysis exhibits that the absence of PHF8 function leads to cognitive impairment and developmental abnormalities specific to the X chromosome among human beings." (PMID 39311138, 2024). "Demethylation of H4K20me1 by Phf8 results in transcriptional suppression of RSK1 and homeostasis of mTOR signaling and causes cognitive impairments." (PMID 37143582, 2023). "Phf8 deficient mice neither display obvious developmental defects nor signs of cognitive impairment." (PMID 28485378, 2017). "However, surprisingly, a recent study showed that Phf8-deficient mice had no obvious developmental defects and cognitive impairment, while Phf8-deficient primary cells had reduced the proliferative potential." (PMID 28665350, 2017).
lung carcinoma (6 papers, 2017 to 2025). "The transcription factor PHF8 was identified as an interacting factor of smoking-related lung cancer using bioinformatics analysis and modeling." (PMID 39311138, 2024). "It is believed that nicotine in tobacco may also induce PHF8 overexpression in lung cancer." (PMID 39311138, 2024).
melanoma (6 papers, 2022 to 2025). A malignant, usually aggressive tumor composed of atypical, neoplastic melanocytes. "Highly expressed PHF8 expression in metastatic melanoma cells is crucial to the activation of the oncogenic pathway and the invasion of melanoma cells through its demethylase activity." (PMID 39311138, 2024). "Through orchestrating a molecular program, PHF8 directly modulates the TGFβ signaling pathway, thereby regulating melanoma invasion and metastasis." (PMID 38813086, 2024). "We show that PHF8 is up-regulated in metastatic samples compared to primary melanomas and nevi from an independent patient cohort and regulates invasive and metastatic potential through a mechanism dependent on its histone demethylase function." (PMID 35179962, 2022). "We stably transduced 451Lu, Colo-679, and 113/6-4L melanoma cell lines with Empty, PHF8 WT, PHF8 F279S, or PHF8 Y14A/W29A-carrying lentiviral particles." (PMID 35179962, 2022). "Through a meta-analysis of gene expression datasets followed by a mini-screen, we identified Plant Homeodomain Finger protein 8 (PHF8), a histone demethylase of the Jumonji C protein family, as a previously unidentified prometastatic gene in melanoma." (PMID 35179962, 2022). "They did not report TGFB1 and its receptors as direct downstream targets of PHF8, as we find in melanoma." (PMID 35179962, 2022). "In summary, we report a mechanism of epigenetic regulation of the TGFβ pathway by PHF8 in melanoma cells that specifically governs melanoma metastasis." (PMID 35179962, 2022). "Transcriptomic and epigenomic analyses revealed that PHF8 orchestrates a molecular program that directly controls the TGFβ signaling pathway and, as a consequence, melanoma invasion and metastasis." (PMID 35179962, 2022). "The precise role of the PHF8-TGFβ signaling axis in immune infiltration of melanoma tumors and response to immunotherapy merits further examination." (PMID 35179962, 2022). "With the aim of ruling out off-target effects, we used orthogonal methods to knock out PHF8 and assess how general the proinvasive effect of PHF8 is across multiple melanoma cell lines." (PMID 35179962, 2022). "We analyzed PHF8 protein expression in a panel of human cultured melanocytes (n = 4), primary (n = 7) and metastatic (n = 11) melanoma cell lines." (PMID 35179962, 2022). "To investigate how PHF8 contributes to the metastatic process, we further delved into the transcriptional changes triggered by PHF8 modulation in melanoma cells." (PMID 35179962, 2022). "Therefore, while all tested candidates merit further characterization of their role in melanoma maintenance and progression, we elected to further examine the role of PHF8 in melanoma invasion and metastasis." (PMID 35179962, 2022). "PHF8 requires its histone demethylase activity to enhance melanoma cell invasion." (PMID 35179962, 2022). "Overall, these data demonstrate that PHF8 directly orchestrates a transcriptional proinvasive program that comprises several components of the TGFβ pathway, activates TGFβ signaling, and promotes melanoma invasion and metastasis." (PMID 35179962, 2022). "In addition, in a subset of 22 patient-matched melanoma samples, we found a statistically significant increase in PHF8 expression from primary to metastasis." (PMID 35179962, 2022). "To further validate PHF8 overexpression in metastatic melanoma, we performed PHF8 immunohistochemistry on an independent cohort of primary (n = 67) and metastatic (n = 46) melanoma patient samples obtained from the New York University (NYU) Langone Health Melanoma Program." (PMID 35179962, 2022). "Furthermore, PHF8 drives melanoma metastasis by specifically enhancing cell invasion." (PMID 38813086, 2024). "Our data suggest that interfering with PHF8 expression might improve response to checkpoint blockade by inhibiting TGFβ signaling, yielding better clinical outcomes in melanoma patients with tumors refractory to programmed cell death protein 1 (PD1) inhibition." (PMID 35179962, 2022).